IL6 (interleukin 6)
Diseases named in the same sentence as IL6 in open-access papers (continued):
Sharing a sentence is not in itself a finding about the gene and the disease.
COVID-19 (continued). "On the contrary, IL-6 (p=0.034), M-CSF (p=0.001) and IP-10 (p=0.023) levels were significantly up-regulated in COVID-19 patients compared with the negative subjects whereas HGF and CTAK demonstrated a tendency to be significantly higher." (PMID 36148234, 2022). "Collectively, we suggest that up-expressed hsa_circ_0000479 could modulate the expression of IL-6 and RIG-I through sponging of hsa-miR-149-5p in COVID-19." (PMID 36081604, 2022). "Nevertheless, the factors determining an IL6 increase in COVID-19 patients have not been well established yet and the association over time between SARS-CoV-2 viremia and IL6, has not been assessed in a prospective cohort with serial samples." (PMID 35783606, 2022). "Increased plasma IL-6, TNF-α, and IL-1β are characteristic of severe COVID-19 patients." (PMID 36298628, 2022). "For example interleukin 6 has been shown to have predictive power for a severe COVID-19 course but was not selected by our algorithms, possibly due to its high number of missing values." (PMID 34279815, 2022). "On the contrary, the present results indicated that IL-6, which has received considerable attention as a biomarker of the progression of COVID-19, is not a predictive factor for the aggravation of COVID-19." (PMID 36282812, 2022). "In particular, IL-6 ≥ 74.98 pg/mL, CRP ≥ 81 mg/L, PCT ≥ 0.56 ng/mL, and D-dimer ≥ 760 ng/mL on admission to the ICU could effectively predict in-hospital mortality in COVID-19 patients." (PMID 35237386, 2022). "Network analysis of inflammatory mediators in the nasal mucosa and serum showed an anti-inflammatory response (IL-10 upregulation) and T2 inflammatory (CCL11 and CCL24 upregulation) response with co-existent inflammation (upregulation of IL-6 and CXCL8) in early COVID-19." (PMID 35397798, 2022). "Severe COVID-19 disease is associated with a so-called “Cytokine Storm”, which is a dramatic increase in inflammatory cytokines/chemokines (especially IL-1β, IL-6, IL-8, and TNF-α) and other inflammatory factors that promote tissue injury and can predict the severity of COVID-19 and survival." (PMID 36296272, 2022). "In this work, we developed the proof of concept for a rapid IL-6 VFA with a wide reportable range that supports its use in a broad spectrum of diseases, including RA, COVID-19-induced CRS, CAR-T therapy-induced CRS, sepsis disease activity, and other inflammatory diseases." (PMID 36140141, 2022). "Moreover, elevated levels of cytokines IL-6, IL-10, and TNF-α were observed in severe COVID-19 patients, directly affecting T-cell subsets and indirectly affecting dendritic cells and neutrophils, thereby reducing lymphocyte count." (PMID 35615369, 2022). "The use of IL-6 as a biomarker of disease severity does not identify IL-6 as a unique contributor to the distinct severe manifestations in COVID-19." (PMID 35280907, 2022). "Although TNF-α is not as relevant as interleukin-6 on the cytokine storm presented in severe COVID-19 patients, anti-TNF-α drug repositioning for COVID-19 has been proposed." (PMID 35432458, 2022). "The use of IL-6 or IL-6R-blocking antibodies in combination with JAK inhibitors to treat COVID-19 patients is also not recommended." (PMID 35306855, 2022). "Thirdly, laboratory findings related to cytokine storm syndrome occurring in severe COVID-19 such as ferritin, interleukin 6 (IL-6), and d-dimer were not included." (PMID 36518574, 2022). "IL-6 ≥ 74.98 pg/mL, CRP values ≥ 81 mg/L, procalcitonin ≥ 0.56 ng/mL, and D-dimer ≥ 760 ng/mL could effectively predict in-hospital mortality in COVID-19 patients." (PMID 35237386, 2022). "Subsequently, Paxlovid was analyzed against the core targets of LUAD/COVID-19 (CXCL2, CCL2, IL12B, CSF3, LBP, IL6, CXCL10) and Paxlovid, and the results showed that IL-6, IL12B, LBP and Paxlovid could be combined." (PMID 36157452, 2022). "Notably, IL-6, IL-1, adhesion molecules, and VEGF have already been reported in many clinical cohort studies of COVID-19." (PMID 35223745, 2022).
COVID-19 (continued). "A recent elegant study showed that CBD downregulated IL-6 and improved the clinical symptoms of ARDS in a mouse model, suggesting that CBD could be an intervention for COVID-19." (PMID 35277472, 2022). "Corticosteroids (Thakur, Datusalia and Kumar, 2022) and various immunomodulators that have some role in the management of COVID-19 include Janus-kinase signal transducers and activators of transcription (JAK-STAT) inhibitors, IL-6 inhibitors, and IL-1 receptor blockers." (PMID 36330085, 2022). "It was already reported that monocytes/macrophages from patients with severe COVID-19 may be the main source of uncontrolled levels of the pro-inflammatory mediators TNF-α and IL-6 in the peripheral blood of the respiratory tract." (PMID 35891437, 2022). "Numerous clinical and laboratory scores that include C-reactive protein (CRP), D-dimer, ferritin, lactate dehydrogenase (LDH), interleukin 6 (IL-6), procalcitonin (PCT), blood urea nitrogen (BUN), creatinine levels and oxygenation (PaO2 and SaO2) have been used for the prognosis of COVID-19." (PMID 35935801, 2022). "The aim of this study was to determine the association of Gal-1 and innate immunity cytokines such as IL-1β, IL-6, IL-10, IL-23, IL-33 with disease severity, alongside with clinical, biochemical features and Chest X-rays (CXR) lung findings in 210 patients with COVID-19." (PMID 35075140, 2022). "The purpose of this study is to research venous thrombosis, interleukin-6 (IL-6) and lymphocyte subsets among cancer patients with COVID-19 and COVID-19 patients with non-cancer." (PMID 36439504, 2022). "An in vitro study examining the anti-inflammatory effects of CBD in alveolar and macrophage models revealed the capacity of CBD to decrease secretion of inflammatory cytokines, such as IL-6, IL-8, CCL2 and CCL7, which are involved in the cytokine storm in severe COVID-19 patients." (PMID 35456990, 2022). "The role of Interleukin-6 (IL-6) has also recently been investigated as a mechanistic explanation driving increased odds of DKA, as IL-6 levels are elevated in both DKA and COVID-19, although this finding may only have prognostic relevance." (PMID 35439266, 2022). "TNF and IL6 are recognized as major factors in the systemic inflammatory immune response, and overexpression of these factors leads to respiratory diseases, including COPD and COVID-19." (PMID 36615255, 2022). "Five variables, including IL8, IL6, IFN-α, and IL17-α, and age with p < 0.1 might play a vital role in the COVID-19 patients' classification." (PMID 36466533, 2022). "For example, IL-6 had not detected an increase at the transcriptional level in the peripheral blood of COVID-19 patients, but there is a large amount of IL-6 protein." (PMID 34975340, 2022). "Indeed, significantly elevated levels of IL-1, IL-6, IL-8, IL-10, IP-10, and TNF-α have been found in the cerebrospinal fluid (CSF) of patients affected by COVID-19." (PMID 35055344, 2022). "Based on this study’s results, taVNS can reduce CRP, IL-6, and depression in patients with COVID-19 but does not interfere in cardiac modulation, COVID-19 clinical symptoms, anxiety, memory, and attention levels." (PMID 36295080, 2022). "Recently, an investigation with a large cohort of patients proposed that serum IL-6 and TNF levels should be considered in the management and treatment of patients with COVID-19 to stratify prospective clinical trials, guide resource allocation and inform therapeutic opportunities." (PMID 35720401, 2022). "Although IL-6 blockade is not the standard strategy for COVID-19 treatment, interleukin-6 remains the best available biomarker for severity assessment and still holds great potential for targeted therapy." (PMID 35405433, 2022). "The counts of lymphocyte subsets decreased and the level of IL-6 increased in ICU COVID-19 patients compared with non-ICU COVID-19 patients." (PMID 35346253, 2022).
COVID-19 (continued). "Other authors who evaluated inflammation in COVID-19 patients presented higher levels of IL-6 in patients admitted to ICU and in those who did not survive." (PMID 35530861, 2022). "In order to further explore the robustness of immune response induced by Janssen COVID-19 vaccine and supplements in BALB/c mice, the present study determined the splenocyte expression of Interleukin-6 (IL-6) and Interleukin-10 (IL-10) cytokines in experimental groups." (PMID 36679902, 2022). "Although IL-6 has been reported to be increased in plasma of COVID-19 patients and higher neutrophilic IL-8 expression was observed in severe COVID-19 cases, we did not detect such trends with our proteomics approach locally in the lung tissue post mortem." (PMID 36526981, 2022). "Two meta-analyses on complicated COVID-19 cases detected higher levels of IL-6 (2.9-fold) compared with those with nonsevere conditions." (PMID 35047633, 2022). "Non-pregnant patients with severe COVID-19 have been found to have greater levels of IL-2, IL-6, IL-7, IL-10, IP-10, MCP-1, TNF-α, macrophage inflammatory protein 1 alpha, and granulocyte-CSF than those with mild and moderate infections." (PMID 36383608, 2022). "Concerning laboratory data, as there was no established protocol to request analytics from patients with COVID-19 at the time the study was carried out, there are insufficient data for some measurements (PCT and IL-6) and they may be subject to bias." (PMID 35210926, 2022). "The differential molecular regulation of IL6 and IL8 might be responsible for severe/moderate versus mild COVID-19 progression." (PMID 36518355, 2022). "High levels of proinflammatory cytokines interleukin 2 (IL-2), IL-6 and IFN-γ were detected in sera of patients with severe COVID-19, suggesting that SARS-CoV-2 may usurp JAK-STAT signaling for pathogenesis." (PMID 35317858, 2022). "Given that some cytokines and chemokines induced by COVID-19 plasma exosomes, such as IL-6 and IL-8, are not typical signature cytokines or chemokines of T cells, we investigated how PRRs of T lymphocytes and monocytes responded to COVID-19 plasma exosomes." (PMID 36526691, 2022). "The interleukin genes IL1RN and IL27 were only upregulated in G2; however, IL6 was not upregulated in either group, corroborating previous observations in lung tissue, despite high levels in the blood of COVID-19 patients." (PMID 35438176, 2022). "The data obtained show that mothers affected by COVID-19 have an increase in pro-inflammatory factors (TNF-α, TGF-β, IL-2, IL-6, IL-8) compared to controls; this increase could generate a sort of “protection of the fetus” from virus attacks." (PMID 35408809, 2022). "Furthermore, Ruxolitinib, a JAK1/JAK2 inhibitor acting downstream of JAK-dependent chemokines/cytokines such as IFN-γ, IL-1β, IL-6, TNF, G-CSF, CXCL9, and CXCL10, has shown promising results in treating COVID-19." (PMID 35269470, 2022). "High levels of IL-6, IL-8, and TNF-α were found in COVID-19 patients’ serum." (PMID 35805406, 2022). "In the evaluation of patients with acute COVID-19, regardless of disease severity, individuals with comorbidities had higher levels of IL-6 (but without statistical significance)." (PMID 35846757, 2022). "The host immune response of COVID-19 presents a signature called “the global immune signature” of SARS-CoV-2 infection, which consists of elevated serum cytokines (particularly IL-1β, IL-6 and TNF-α), impaired IFN responses, and peripheral lymphopenia as markers of severe disease." (PMID 35982454, 2022). "Interleukin (IL)-1, IL-6, IL-10, tumor necrosis factor-alpha (TNF-a), interferon-gamma (IFN-γ), chemokine (C-C motif) ligand 2 (CCL-2), CXCL-9, and IL-8 are some of the additional cytokines found to be important in the pathophysiology of COVID-19." (PMID 35632654, 2022). "Similarly, high-level cytokines (e.g., IL-1β, IL-6, IL-8, IL-10, IFN-γ, and TNF-α, etc.)were registered in the blood of Coronavirus Disease 2019 (COVID-19) patients." (PMID 35350754, 2022).
COVID-19 (continued). "Plasma IL-6 is highly elevated, but GM-CSF is suggested to be a particular feature of severe cases of COVID-19, as it not found in patients who have died from influenza virus infection." (PMID 35204803, 2022). "Accordingly, the effects of gender, age, DM, and HT on the salivary levels of IL-6, CRP, and CXCL-10 observed in SARS-CoV-2 patients might be consequences of their impacts on COVID-19 disease severity." (PMID 35967091, 2022). "This suggests that IL-6 does not play the key role in the development of inflammatory and thrombosis processes in COVID-19, but rather is just one more factor added to the COVID-19 physiopathology." (PMID 35053224, 2022). "First, the collective profile of cytokines produced matches three core cytokines of the COVID-19 cytokine storm, IL-1β, IL-6, and IL-8, with no anti-inflammatory cytokines produced." (PMID 36296272, 2022). "The plasma level of IL-6, a significant cytokine contributing to macrophage activation syndrome (MAS), which is also known as a form of CRS, has been shown to increase in both mild and severe COVID-19 patients." (PMID 35223745, 2022). "As IL-6 is immobilized on these NPs, significant macrophage (Mφ) suppression occurs, which might lead to the therapeutic use of NPs for CRS in COVID-19 patients." (PMID 36463213, 2022). "Recently, studies also showed that the level of IL-6 in severe cases was markedly higher than that in mild and moderate cases, but the levels of CD4+ T cells, CD8+ T cells and NK cells were decreased, indicating immunosuppression in severe COVID-19 patients." (PMID 35270015, 2022). "Patients with COVID-19 showed lower IL-3 and higher IL-6 concentrations in plasma than noninfected controls." (PMID 36129990, 2022). "Although we currently do not know the exact mechanism by which IL-6 is associated with NAFLD and COVID-19." (PMID 36380355, 2022). "Moreover, after nicotine+SARS-CoV-2 treatment, cells released high levels of TNFα, IL6, IL8, and IL10, similarly to what is observed in COVID-19 patients with high disease severity and mortality." (PMID 36012747, 2022). "Our findings are in alignment with previous studies on serum IL-6, but, moreover, they suggest that the source of elevated serum IL-6 levels in COVID-19 ICU patients is not PBMCs and neutrophils." (PMID 36363785, 2022). "Our data show that the levels of these IL-1α, IL-1β IL-6 and IL-18 cytokines are significantly lower in severe COVID-19 survivors than in non-survivors." (PMID 36142255, 2022). "COVID-19 patients exhibit unique coagulopathy, characterized by thrombus formation with elevated levels of cytokines, including tumor necrosis factor (TNF)-α, interleukin (IL)-8, and IL-6, among others." (PMID 36466841, 2022). "High levels of IL-1β, IL-6, and TNF-α in hyperinflammatory conditions, which are strong inducers of hyaluronidase, lead to the production and accumulation of HA in the alveolar spaces in severe COVID-19 patients." (PMID 35741101, 2022). "CP therapy can reduce mortality and improve breath and inflammatory cytokines IL-6 and Ferritin in COVID-19 with no significant increase in adverse reactions." (PMID 36248407, 2022). "A selected set of systemic mediators (IL-6, IFN-γ, IL-1Ra, IL-13, PDGF and IL-7) were identified as putative laboratory markers, applicable as complementary records for the clinical management of patients with severe COVID-19." (PMID 36451835, 2022). "Previous studies have shown that proinflammatory markers, including IL-6, IL-8, IL-1β, and TNFα, are significant predictors of COVID-19 disease severity, regardless of demographics or comorbidities." (PMID 36865568, 2022). "suggest that IL6 and IL12B play a role in the development of COVID-19." (PMID 36157452, 2022). "The mean levels of TNF-α were higher in COVID-19 patients, in the age group 51-80 years old than the age group 20-50 years, whereas IL-6, testosterone, and inhibin B levels were not significantly different between 20-50 years and 51-80 years subgroups." (PMID 36381078, 2022).
COVID-19 (continued). "Multivariate COX regression analysis revealed that NEAT1 is an independent predictor for survival among COVID-19 patients with an odds ratio of 7.48 and 95% CI (1.03 - 36.08) (P=0.02) while (male sex, smokers, CCL2, TNF-α, and IL-6) were cofactors affecting overall survival." (PMID 35982898, 2022). "The cytokine profile obtained was adequate because it mainly involved anti-viral cytokines IL-12, IL-17A, and IL-2, not cytokines participating in the COVID-19 cytokine storm, such as IL-6 or IL-10." (PMID 35440789, 2022). "We demonstrate that IL-6 signalling-related biomarkers (IL-6, sIL-6R, sgp130, IL-6 trans-signalling estimated by the B/T complex ratio and the FME) can predict the evolution of the disease in COVID-19 patients." (PMID 35634332, 2022). "COVID-19; SARS-CoV-2; Neopterin; CRP; IL-6; Viral infection; Biomarker." (PMID 35529699, 2022). "As for the second signal, LNPs designed in a similar fashion as for the COVID-19 mRNA vaccines—but without mRNA—induced a strong pro-inflammatory cytokine profile (including IL-1β and IL-6) in mice upon injection into the skin." (PMID 35890284, 2022). "The severity of the illness and the levels of serum cardiac biomarkers (CK, CK-BM, cTnI), as well as the inflammation markers (IL-1, IL-6, CRP), were lesser in hypertensive COVID-19 patients treated with AT1R blockers than those treated with other antihypertensive drugs." (PMID 34973134, 2022). "Reinold et al3 reported that proinflammatory cytokines such as interleukin-6 were high and the anti-inflammatory response was suppressed in severe COVID-19 patients compared to non-severe COVID-19 patients." (PMID 36098357, 2022). "In the post-COVID-19 group, subjects with long COVID-19 had higher levels of IL-17 and IL-2 (p<0.05), and subjects without sequelae had higher levels of IL-10, IL-6 and IL- 4 (p<0.05)." (PMID 35846757, 2022). "Here, we report that plasma exosomes of COVID-19 patients contain SARS-CoV-2 double stranded RNA (dsRNA) and stimulate robust production of interleukin-6 (IL-6), IL-8, tumor necrosis factor-α (TNF-α), and other inflammatory cytokines and chemokines by human peripheral mononuclear cells." (PMID 36526691, 2022). "In previous study, it was found elevated serum level of IL-6 in COVID-19 patients with diabetes compared with those without diabetes." (PMID 37359706, 2022). "ADAM17 mediates shedding of ACE2, IL-6 and TNFα, and suppression of ADAM17 may therefore modulate the cytokine storm that has been identified in patients with severe COVID-19." (PMID 35269582, 2022). "High serum cytokines, such as interleukin-6 (IL-6), inflammatory serum markers, such as ferritin, D-dimer, C-reactive protein (CRP), and peripheral lymphopenia are some characteristics of immunological signatures of COVID-19." (PMID 35458517, 2022). "Coherently, another study conducted on postmortem lung specimens of hospitalized patients confirmed that IL-6 expression is not increased in COVID-19 patients’ lungs, which are the main site of infection leading to morbidity and mortality." (PMID 36422642, 2022). "The plasma concentration of TNFα correlated with the surface expression of CD47 when the COVID-19 and Control groups were pooled for analysis, whereas the concentration of IL-6 in plasma did not correlate with CD47 expression in any group." (PMID 36466824, 2022). "Significantly, by comparing survivors and non-survivors of COVID-19, it was observed that IL-6 plays a more important role in mortality than the other increased inflammatory factors." (PMID 36091037, 2022). "The network pharmacology results showed that Yinqiao powder may inhibit the inflammatory response by suppressing IL-6, CXCL2, TNFα, NF-κB, etc., in the treatment of COVID-19." (PMID 36467981, 2022). "Interestingly, major cytokines like IL-6 and TNF-α involved in the severe COVID-19 cases are the downstream products of the TLR4 signaling pathway." (PMID 35812188, 2022).